MMP9 (matrix metallopeptidase 9)
Diseases named in the same sentence as MMP9 in open-access papers (continued):
Sharing a sentence is not in itself a finding about the gene and the disease.
diabetic retinopathy (continued). "Thus, our results suggest that metalloproteinase inhibitor 1 may influence the development of diabetic retinopathy and combined with high levels of MMP-9 may drive the progression towards the proliferative phase." (PMID 27280065, 2016). "In research on diabetic retinopathy, VEGF and MMP-9 are shown to regulate ZO-1 and occludin in retinal vascular endothelial cells; however, in this study, we discovered a novel signaling pathway that can modulate ZO-1 and occludin." (PMID 37430272, 2023). "In contrast to their involvement in early stages of diabetic retinopathy, increased levels of MMP-2 and MMP-9 facilitate angiogenesis in the later stage of the disease through multiple proposed mechanisms." (PMID 31398819, 2019). "Elevations of MMP-9 have been recorded in diabetic individuals, with both T2DM and diabetic retinopathy, and correlated with increased severity of T2DM." (PMID 30149671, 2018). "However, in light of recent advances in our understanding of GPCR-biased agonism, perhaps another explanation could be that increased levels of GPCR agonists are contributing to the activation of MMP-9, which could partially account for its role in diabetic retinopathy." (PMID 30149671, 2018). "Our data suggest that MMP-9 and VEGF are key therapeutic targets of EGCG for treatment and prevention of ocular angiogenic diseases such as age-related macular degeneration, diabetic retinopathy, and corneal neovascularization." (PMID 25123184, 2014). "Thus, MMP-9 and MMP-14 protein levels can be used for the diagnosis and treatment in diabetic retinopathy." (PMID 35729613, 2022). "Thus, treatments targeting the inhibition of MMP-9 and MMP-14 can be used in the treatment of diabetic retinopathy." (PMID 35729613, 2022). "Due to the higher levels of MMP-9 and MMP-14 in the pathogenesis of diabetic retinopathy, these proteins may probably be among the therapeutic targets in the prevention and treatment of retinopathy." (PMID 35729613, 2022). "Inhibition of the MMP-9 and MMP-14 proteins may be an alternative for suppressing diabetic retinopathy." (PMID 35729613, 2022). "Activation of SIRT1 by Resveratrol maintains the epithelial barrier by increasing the expression of TJ proteins ZO1, Occludin and Claudin1, while it negatively regulates MMP9 in diabetic retinopathy, and reduction of SIRT1 levels through oxidative stress confers an increase in MMP9." (PMID 39086962, 2022). "Quercetin could reduce the expression of MMP-9 and VEGF in rats with diabetic retinopathy and inhibit the generation of angiogenesis both in vitro and ex vivo." (PMID 33204295, 2020). "In the early stage of diabetic retinopathy, increased levels of MMP-2 and MMP-9 may promote vascular permeability by degrading tight junction proteins, thus disturbing the tight junction complex." (PMID 31398819, 2019). "It attenuates diabetic retinopathy by alleviating retinal inflammation through upregulation of SOCS3 expression, suppression of toll-like receptor 4 (TLR4) signaling, and reduction of MMP-9 production, and of inflammatory factors including TLR4/p38/NF-κB signaling pathways in BV2 cells." (PMID 29937497, 2018). "Recently, Jayashree reported that MMP-9 was shown to be significantly increased in patients with T2DM with diabetic retinopathy compared to individuals with T2DM without retinopathy." (PMID 30149671, 2018). "Consistent with the results from in vitro and in vivo models, H3K27me3 levels were elevated by over 2.5-fold and Ezh2 binding was increased by approximately 4-fold at the MMP-9 promoter in microvessels from donors with diabetic retinopathy compared with their age-matched nondiabetic donors." (PMID 29261844, 2017). "Importantly, our results suggest that MMP-9 and VEGF is one of the noteworthy therapeutic targets of EGCG for treatment and prevention of ocular angiogenic diseases, such as age-related macular degeneration, diabetic retinopathy, and corneal neovascularization." (PMID 25123184, 2014).
diabetic retinopathy (continued). "Inhibition of MMP-9 and MMP-2 with COX inhibitors prevents retinal pathologies, but there is no clinical study on the treatment of diabetic retinopathy patients with MMP inhibitors." (PMID 35729613, 2022). "Thus, we aimed to compare MMP-9 and MMP-14 levels in diabetic and non-diabetic patients which could be the biomarkers of diabetic retinopathy." (PMID 35729613, 2022).
fibrosarcoma (64 papers, 2002 to 2025). A malignant mesenchymal fibroblastic neoplasm affecting the soft tissue and bone. "Interestingly, previous studies demonstrated a possible association between TEM1 and MMP-9 in fibrosarcoma cells." (PMID 36639546, 2023). "An in vivo study showed the possible association between TEM1 and MMP-9 in fibrosarcoma cells." (PMID 36639546, 2023). "The HT-1080 cell line used in this study is a fibrosarcoma cell line, bearing an NRAS mutation, and also expressing high levels of MMP-9, which contributes to its invasiveness." (PMID 39519810, 2024). "In contrast, resveratrol significantly increased MMP-9 activity and expression and improved cell motility in fibrosarcoma, promoting disease progression." (PMID 39335164, 2024). "Recently, it has been demonstrated that 21 inhibits matrix metalloproteinase-9 (MMP-9) activity, as well as the invasion and migration of human fibrosarcoma cells in vitro, via Ca-dependent signaling pathways." (PMID 37242514, 2023). "Previous studies showed that indacaterol inhibited cell migration and invasion of fibrosarcoma cells with a reduction of TNFα – induced MMP-9 expression." (PMID 37904233, 2023). "In this research, we have investigated the influence and mechanism of GNP (sulfated polysaccharide from Gelidium crinale) on tumor metastasis and MMP-9 expression of human fibrosarcoma (HT1080) cells." (PMID 35954126, 2022). "In the only inconsistent study, Gweon and Kim reported that resveratrol at different concentrations increased the activity and expression of MMP-9 in human fibrosarcoma cells." (PMID 33723310, 2021). "A study found that 100 μM eugenol has an antioxidant effect on human fibrosarcoma cells, and can inhibit MMP-9 activity and expression." (PMID 30518369, 2018). "In particular, transient and dose-dependent upregulation of extracellular MMP-2 and MMP-9 have been observed in irradiated cell lines derived from pancreatic cancer, glioma, lung cancer, melanoma, fibrosarcoma, and hepatocarcinoma." (PMID 30105016, 2018). "Both miR-520c and miR-373 confer robustness to biological processes by upregulation of activity of MMP9 in human fibrosarcoma cells." (PMID 25774514, 2015). "It has been experimentally demonstrated that the standardized aRVS extract has antiangiogenic activities by inhibiting VEGF and an inhibitory effect on matrix metalloproteinase-2 (MMP-2) and MMP-9 activities in a human fibrosarcoma cell line." (PMID 23710214, 2013). "Sensitivity to doxycycline was nearly equivalent in MMP-2 expression, but fibrosarcoma expression of MMP-9 was significantly more sensitive to doxycycline than were the other cell lines." (PMID 24085323, 2013). "Functionally, CD97 has been shown to promote cell migration and invasion, as well as increase expression and secretion of matrix metalloproteinase-2 (MMP2) and MMP9 in the fibrosarcoma cell line HT1080." (PMID 23658650, 2013). "In this study, we investigated the effects of selected cytokines, inducers and inhibitors affecting cancer cell metabolism on the regulation of MMP-2 and MMP-9 activities in chondrosarcoma, fibrosarcoma, liposarcoma and synovial sarcoma cell lines." (PMID 24085323, 2013). "Table III shows the quantitative densitometry results from the effects of natural inhibitors EGCG, the NM and retinoic acid on MMP-2 and MMP-9 expression in chondrosarcoma, fibrosarcoma, liposarcoma and synovial sarcoma cell lines." (PMID 24085323, 2013). "We examined the effect of cytokines, mitogens, inducers and inhibitors on MMP-2 and MMP-9 secretion in chondrosarcoma (SW-1353), fibrosarcoma (HT-1080), liposarcoma (SW-872) and synovial sarcoma (SW-982) cell lines." (PMID 24085323, 2013). "IFN-γ or IFN-β was also suggested to inhibit the expression of MMP-9 in human astroglioma and fibrosarcoma cell lines, as well as in primary astrocytes, supposable by the modulation of transcription factors that regulate the MMP-9 transcription." (PMID 24023566, 2013).
fibrosarcoma (continued). "In the present study we identify a novel mechanism for repression of MMP-9 transcription by IFNβ in HT1080 fibrosarcoma cells." (PMID 22879913, 2012). "Of these sites, synergistic activation via the Sp1, NF-κB and proximal AP-1 site is required for full activation of the MMP-9 promoter by PMA in human fibrosarcoma cell line HT1080." (PMID 22879913, 2012). "It has been demonstrated that MMP-9-CD44-EGFR interaction and the dimerization of the MMP-9 hemopexin domain are critical to the migration of fibrosarcoma cells." (PMID 21749678, 2011). "Moreover, in TPA-induced HT-1080 fibrosarcoma cells, XN suppressed both the activation and expression of MMP-9 and MMP-2, reduced the MT1MMP mRNA level, and induced a substantial TIMP-1 and TIMP-2 depletion." (PMID 34204745, 2021). "We previously reported that SMYD3 regulates Mmp-9 transcription in fibrosarcoma cells." (PMID 33244033, 2020). "Both RBE (−54) and AP-1 (−79) elements regulate v-Src induced gelatinase B/MMP-9 transcription in fibrosarcoma cells, c-Ha-Ras induced gelatinase B/MMP-9 transcription in adenocarcinoma cells and c-Ha-ras/v-myc-induced gelatinase B/MMP-9 transcription in rat embryo cells." (PMID 24473089, 2014). "MMP-2 and-9 expression of chondrosarcoma and fibrosarcoma cells treated with TNF-α 10 ng/ml were downregulated by NM treatment in a dose-dependent manner with MMP-2 block at 1000 μg/ml NM and MMP-9 total block at 500 μg/ml NM in fibrosarcoma and 99% block at 1000 μg/ml in chondrosarcoma." (PMID 24085323, 2013). "This outcome accords with the results of Sato and co-workers, where the secretion of MMP-9 could be prevented by nobiletin (a flavonoid) or LY294002 in fibrosarcoma cells." (PMID 19331685, 2009). "A previous study on fibrosarcoma cells showed an increase in MMP9 activity could be explained by miR-520c and miR-373 that acts by targeting the 3’UTR of mTOR and SIRT1 and its downstream effectors and kinases to inactivating signaling pathways that negatively regulate MMP9 expression." (PMID 25774514, 2015). "Moreover, NF-κB increased MMP9 expression and enhanced the migration of fibrosarcoma cells." (PMID 25424420, 2014). "In fibrosarcoma, ISOGK hindered the expression of MMP9 by disrupting NF-κB signaling, consequently impeding the invasion of HT1080 cells." (PMID 40225566, 2025). "Specifically, it inhibits MMP-1, MMP-3, MMP-7, MMP-9, and MMP-14, which hinders the expansion of HUVECs and the activated process of proMMP-2 regulated by MMP-14 in human fibrosarcoma cells." (PMID 38611849, 2024). "Under hypoxia, NCL regulates the expression of matrix-metalloproteinase-9 (MMP-9) and collagen prolyl 4-hydroxylase-alpha(I) (C-P4H-alpha(I)), which are involved in ECM remodeling in human fibrosarcoma cells." (PMID 36899956, 2023). "Inhibits MMP-2 and MMP-9, which play an important role in cancer progression, in HT1080 fibrosarcoma cells." (PMID 35208993, 2022). "Given that an MMP-cleaved CPP-Dox can inhibit proliferation in Dox-resistant cancer cell lines, this ELP-mmpL-CPP-Dox system was further validated using HT-1080, a fibrosarcoma cancer cell producing endogenous MMP-2 and MMP-9." (PMID 33498762, 2021). "The HT1080 cell line is derived from a human fibrosarcoma to mimic stromal fibroblasts and is sustained to express MMP-2 and MMP-9." (PMID 33926142, 2021). "The ethanol extract of baked Gardeniae fructus inhibited the expression of MMP9 and MMP13, thereby suppressing the migration and invasion of human fibrosarcoma cells." (PMID 34643237, 2021). "In human fibrosarcoma cells (HT-1080), TPL can modulate the expression and activity of both MMP-2 and MMP-9, and it can reduce invasiveness by directly lowering MMP-9 gene expression and activity." (PMID 27073100, 2017). "HDAC1 was shown to be recruited to the MMP-9 promoter site, reducing histone H3 acetylation and NF-κB recruitment, leading to repression of MMP-9 expression in fibrosarcoma cells." (PMID 28596772, 2017).
fibrosarcoma (continued). "In support of this, gelatinase B/MMP-9 expression correlates with the intravasation and metastatic dissemination of HT-1080 fibrosarcoma cells, which is inhibited by the gelatinase B/MMP-9 inhibitor marimistat." (PMID 24473089, 2014). "On gelatinase zymography, fibrosarcoma, chondrosarcoma, liposarcoma and synovial sarcoma showed bands corresponding to MMP-2 and MMP-9 with enhancement of MMP-9 with PMA (100 ng/ml) treatment." (PMID 23661254, 2013). "We found that fibrosarcoma HT-1080, chondrosarcoma SW-1353, liposarcoma SW-872 and synovial sarcoma SW-982 normally expressed both MMP-2 and MMP-9." (PMID 24085323, 2013). "IL-1β stimulated MMP-9 and MMP-2 in chondrosarcoma cells, enhanced levels of both MMPs at 1 ng/ml but decreased levels at 25 ng/ml in fibrosarcoma, inhibited MMP-2 and enhanced MMP-9 at 1 and 10 ng/ml and downregulated at 25 ng/ml in liposarcoma cells." (PMID 24085323, 2013). "Fibrosarcoma, chondrosarcoma, liposarcoma and synovial sarcoma showed bands corresponding to MMP-2 and MMP-9 with dose-dependent enhancement of MMP-9 with phorbol 12-myristate 13-acetate (PMA) treatment." (PMID 24085323, 2013). "IL-1β had a slight inhibitory effect on fibrosarcoma, liposarcoma and synovial sarcoma MMP-2 and MMP-9 except for MMP-9 in synovial sarcoma which showed slight stimulation." (PMID 24085323, 2013). "Liposarcoma showed block of MMP-2 at 500 μg/ml and MMP-9 at 1000 μg/ml, while fibrosarcoma and chondrosarcoma showed block of MMP-2 at 1000 μg/ml and virtual block of MMP-9 at 1000 μg/ml." (PMID 24085323, 2013). "Conversely, it has been reported that in HT-1080 human fibrosarcoma cells where Kp signaling is anti-invasive, expression of KISS1 results in the negative regulation of MMP-9 production." (PMID 21738726, 2011). "In addition, miR-373 was also found toup-regulate MMP-9 by regulating SIRT1, leading to activation of the RAS/RAF/MEK/ERK pathways in fibrosarcoma cells." (PMID 34096221, 2021). "In keratinocytes, down-regulation of CD9 was found to increase activity and expression of MMP9 through JNK signaling, while in a fibrosarcoma cell line, epithelial growth factor receptor, EGFR, was an important intermediary for increased release of pro-MMP9 by CD9." (PMID 25889530, 2015). "MMP-2 and-9 expression of chondrosarcoma and fibrosarcoma cells treated with IL-1β 10 ng/ml were downregulated by NM treatment in a dose-dependent manner with MMP-2 block at 1000 μg/ml NM and MMP-9 total block at 100 μg/ml NM in fibrosarcoma and at 1000 μg/ml in chondrosarcoma." (PMID 24085323, 2013). "NAMI-A can directly inhibit the enzymatic activity of MMP-2 and MMP-9, as shown by the zymography performed with conditioned medium of fibrosarcoma (HT-1080) and neuroblastoma (SK-N-BE) tumour cells (data not shown)." (PMID 11953835, 2002). "Previous studies have also shown suppression of MMPs in response to IFN-γ, such as MMP-9, which like MMP-1 and MMP-3, also contains AP-1 sites (two) and putative SBEs58–60, and has been shown to be repressed following IFN-γ treatment in astrocytes, fibrosarcomas, and monocytes." (PMID 28819304, 2017). "miR-520c and miR-373 upregulate MMP-9 expression and enhance human fibrosarcoma cell migration and growth not by direct binding to the MMP-9 promoter, but by directly targeting the 3′-UTR of the mRNAs of mTOR and SIRT1, which are negative regulators of MMP-9 expression." (PMID 23509776, 2013). "Moreover, treatment of Wehi-164 fibrosarcoma cells with aqueous extract of spearmint led to significant reduction in MMP-2/MMP-9 activity in a dose-dependent manner, as there was no detectable activity of MMP-2/MMP-9 in Wehi-164 cells treated with 10 mg/mL of the extract after 24, 48, and 72 h." (PMID 33672486, 2021).